CD14 (CD14 molecule)
Diseases named in the same sentence as CD14 in open-access papers (continued):
Sharing a sentence is not in itself a finding about the gene and the disease.
Candida infection (1 paper, 2017). "The CD14+ cells also decreased over time after Candida infection." (PMID 27799331, 2017).
cardiac arrest (1 paper, 2021). Cessation of breathing and/or cardiac function. "We report the composition of monocyte subpopulations and the expression of CD14 and HLA-DR following cardiac arrest." (PMID 34117334, 2021). "Expression analyses of CD14 and mHLA-DR were performed to further characterize the inflammatory response following cardiac arrest." (PMID 34117334, 2021). "However, the extent to which CD14 expression was upregulated at 24 h following cardiac arrest was significantly correlated with the time to ROSC (rs: 0.650; p: 0.001)." (PMID 34117334, 2021). "In line with the hypothesis that CD14 might be involved in systemic inflammation after cardiac arrest, we now observed progressive upregulation of CD14 within 24 h following ROSC." (PMID 34117334, 2021). "Our observation of a significant correlation between the level of CD14 expression and the duration from collapse to ROSC supports a possible relationship between the extent of ischemia–reperfusion injury following cardiac arrest and subsequent monocyte activation." (PMID 34117334, 2021).
Chagas cardiomyopathy (1 paper, 2020). A disease of the cardiac muscle developed subsequent to the initial protozoan infection by trypanosoma cruzi. "We aimed to investigate the association of CD14 -260C/T (rs2569190) polymorphism and Chagas cardiomyopathy and the functional characteristics of CD14+ and CD14- monocytes upon infection with Trypanosoma cruzi." (PMID 33146244, 2020). "Thus, differential CD14 expression may have an important influence in the development of Chagas cardiomyopathy." (PMID 33146244, 2020).
Chlamydia infection (1 paper, 2010). "Prostate epithelial cells are thought to be early sensors of infection and CD14 and toll-like receptor 4 (TLR4) production in these cells contributes to protection from Chlamydia infection." (PMID 20070897, 2010).
chronic GVHD (1 paper, 2014). "By contrast, patients who developed chronic GVHD had received lower numbers of conventional CD14+CD16− monocytes (3.76×106/kg, 1.7-10.1) compared with children without chronic GVHD (11.45×106/kg, 0.6-144.2; p = 0.016]." (PMID 25179788, 2014).
chronic idiopathic urticaria (1 paper, 2023). Chronic form of idiopathic urticaria. "Interestingly, a decreased TLR-4 expression on CD14+ cells from chronic idiopathic urticaria patients was observed in ex vivo conditions." (PMID 38045687, 2023).
chronic otitis media (1 paper, 2024). Chronic form of otitis media (disease). "We analyzed the impact of the natural plant-derived monoterpene oxide 1,8-Cineol on the cellular characteristics of circulating CD14/CD16 monocyte subsets in the peripheral blood of patients with chronic otitis media (COM) using flow cytometry." (PMID 38541021, 2024).
colon adenoma (1 paper, 2022). An adenoma that arises from the colon. "Considering inhibition of M2 polarization is CD14 dependent, downregulation of CD14 reprograms macrophages to M2 polarization which could support malign transformation and tumor associated microenvironment in colon adenomas through immune evasion and cytokine profile." (PMID 35486660, 2022).
complex regional pain syndrome (1 paper, 2014). A chronic pain syndrome characterized by a disproportionate spontaneous or stimulus-induced pain, accompanied by a variably mixed myriad of autonomic and motor disorders including symptoms such as swelling, allodynia, skin blood supply and trophic disturbances. "Elevated blood levels of inflammatory monocytes (CD14+CD16+) are present in patients with complex regional pain syndrome." (PMID 24499354, 2014).
congenital toxoplasmosis (1 paper, 2014). Toxoplasma infection that is present from birth. "An increase in proinflammatory monocytes (CD14+CD16+HLA-DR++) in infants with congenital toxoplasmosis was observed." (PMID 25328286, 2014).
coronary stenosis (1 paper, 2020). Narrowing of the coronary artery lumen diameter. "Patients with stenosis <70% tended to have higher frequency of CD14+CD16hi monocytes compared to patients with coronary artery stenosis >70%." (PMID 33854919, 2020). "Analysis of monocytes’ subpopulation revealed that patients with stenosis <70% tended to have the higher frequency of non-classical CD14+CD16hi monocytes compared to patients with coronary artery stenosis >70%." (PMID 33854919, 2020).
crescentic glomerulonephritis (1 paper, 2022). A histopathologic term for a pattern of diseases characterized by extensive crescent formation in the glomeruli; patients present clinically with rapid deterioration of renal function, and possible progression to end-stage renal failure within weeks or months. "In response to crescentic glomerulonephritis, seven transcriptionally distinct subpopulations of macrophages/monocytes were identified, including two groups of Cd14+ monocytes (Cluster 0, 1) and five clusters of Adgre1+ (F4/80) macrophages (Cluster 3, 4, 7, 8, 9)." (PMID 35484716, 2022).
cutaneous leishmaniasis (1 paper, 2025). Leishmaniasis affecting the skin. "This study provides novel insights into the immunopathogenesis of human cutaneous leishmaniasis (CL), demonstrating that Leishmania (Viannia) braziliensis distinctly modulates the release of extracellular vesicles (EV), including those derived from CD4+, CD8+, and CD14+ immune cells." (PMID 40872281, 2025).
cutaneous vasculitis (1 paper, 2022). Inflammation of the blood vessel wall characterized by palpable purpura. "Mast cells contribute to the pathogenesis of cutaneous vasculitis through complement C3 that is cleaved to C3b and then to iC3b by complement factor I. The receptor of iC3b, CD11b, is expressed on neutrophils and monocytes and CD14 on monocytes." (PMID 35747245, 2022).
cyst (1 paper, 2023). A sac-like closed membranous structure that may be empty or contain fluid or amorphous material. "Furthermore, cyst fluid and immunoprecipitated urine from a small number of ADPKD patients (n = 16) showed increased expression of soluble forms of CD14." (PMID 38027263, 2023).
cystic kidney disease (1 paper, 2012). A congenital or acquired kidney disorder characterized by the presence of renal cysts. "Some proteins included in DPL have previously been linked to the progression of cystic kidney disease, for example CD14 molecule." (PMID 23228063, 2012).
delirium (1 paper, 2017). A disorder characterized by confusion; inattentiveness; disorientation; illusions; hallucinations; agitation; and in some instances autonomic nervous system overactivity. "Adjusting the association between prophylactic HS and delirium by CD14 + CD16+ monocytes showed a reduction in effect size." (PMID 29137628, 2017). "Prophylactic HS (independent variable) was associated with delirium (dependent variable) and with CD14 + CD16+ monocytes (mediating variable)." (PMID 29137628, 2017). "Delirium remained significantly related to CD14 + CD16+ monocytes (odds ratio [OR], 14.51; 95% CI, 2.41 to 87.38; P = 0.004)." (PMID 29137628, 2017). "The effect of HS on the probability of delirium decreased (odds ratio [OR], 0.86; 95% CI, 0.14 to 5.33; P = 0.874) when accounting for CD14 + CD16+ monocytes." (PMID 29137628, 2017). "When the association between HS and delirium was controlled for CD14 + CD16+ monocytes, the effect size became nonsignificant (odds ratio [OR], 0.86; 95% CI, 0.14 to 5.33; P = 0.874)." (PMID 29137628, 2017). "In addition, logistic regression analysis demonstrated the strong association between CD14 + CD16+ monocytes and delirium." (PMID 29137628, 2017). "HS and CD14 + CD16+ monocyte levels were set as the independent variables, and delirium was set as the dependent variable." (PMID 29137628, 2017).
diabetic macular edema (1 paper, 2025). "Another study is utilizing soluble CD14 as a surrogate biomarker to assess the anti-inflammatory effects of apixaban in reducing diabetic macular edema (DME)." (PMID 41283645, 2025).
diarrhoea (1 paper, 2022). "Some of the DEGs in diarrhoea-susceptible sheep, enriched in GO terms and sub-network analysis, included IL-6, LOC101121216 (serum amyloid A), SIGLEC1, CHI3L1, S100A9, CD14, CD68, CD86, Ovar-DRB1, IL1RL1, LOC101103238 (CXCL5), CCL22 and IL1RN." (PMID 35576023, 2022).
diffuse midline glioma (1 paper, 2024). A diffuse glioma that arises from the midline structures of the central nervous system. "This hypothesis-generating study characterized the mRNA expression profiles and prognostic impacts of antigen-presenting cell (APC) markers (CD14, CD163, CD86, and ITGAX/CD11c) in pediatric brainstem diffuse midline glioma (pbDMG) tumors." (PMID 38255296, 2024).
dry eye (1 paper, 2018). "The only leukocyte population that significantly increased (a twofold increase) in dry eye patients compared to controls was the monocyte/macrophage population (CD14+ cells)." (PMID 29673232, 2018). "In addition, the higher CD4/CD8 ratio and the increased percentages of CD14+ (monocytes/macrophages) observed in dry eye patients could be due to the effect of the conjunctival release of pro-inflammatory cytokines and chemokines." (PMID 29673232, 2018).
dyspepsia (1 paper, 2013). An uncomfortable, often painful feeling in the stomach, resulting from impaired digestion. "A case-control study comprising 284 ethnic Chinese individuals (70 non-cardia GC cases and 214 functional dyspepsia controls) was conducted for the genotyping of TLR2 -196 to -174del, CD14 -260 C/T and TLR4 rs11536889 using PCR, RT-PCR and mass spectrometry." (PMID 23565226, 2013).
Ebola virus disease (1 paper, 2024). "In a rhesus macaque model of Ebola virus disease, a shift from CD16+ to CD14+ macrophages was observed in the liver." (PMID 39635525, 2024).
ependymoma (1 paper, 2021). A WHO grade II, slow growing tumor of children and young adults, usually located intraventricularly. "To explore the ontogenies of TAM subsets in spinal ependymomas, we employed RNA velocity analysis and identified two different origins of CD44+ TAMs, including both CD14+ monocytes and CX3CR1+ TAMs." (PMID 34824203, 2021).
folate deficiency (1 paper, 2024). A nutritional condition produced by a deficiency of FOLIC ACID in the diet. "However, folate deficiency induced a stronger inflammatory response, as evidenced by elevated CD14 expression and increased release of CCL2 and TNFα in cells with low folate levels compared to those with normal levels." (PMID 38881906, 2024).
G6PD deficiency (1 paper, 2017). An X-linked genetic condition caused by alterations in the gene G6PD that result in moderately to severely decreased activity levels of the enzyme glucose-6-phosphate dehydrogenase. "After having excluded samples with mixed Plasmodium infections, G6PD-deficiency, or hemoglobin C, samples of CD14+ (monocytes) and CD14– (~98% lymphocytes) cells from infected and uninfected Fulani and Mossi individuals were selected for RNA-sequencing and DNA-methylation analyses." (PMID 28923166, 2017).
gangrene (1 paper, 2016). Death of tissue, usually in considerable mass and generally associated with loss of vascular (nutritive) supply and followed by bacterial invasion and putrefaction. "Yet, patients with advanced stages of PAOD suffering from ischemic rest pain or gangrene/tissue loss had significantly increased expression of CD106 on “classical” CD14++CD16− monocytes (r = 0.559, p < 0.001)." (PMID 27991581, 2016).
Giardia (1 paper, 2018). "Since Giardia-infection may stimulate macrophages, we further defined monocytes as CD14+CD16+ and CD14+CD16- cells and observed significant lower number of CD14+CD16+ population at week 2 (p<0.0001), week 6 (p<0.0001) and week 14 (p<0.0001) as compared to controls." (PMID 30412580, 2018).
gingival overgrowth (1 paper, 2018). Excessive growth of the gingiva either by an increase in the size of the constituent cells (gingival hypertrophy) or by an increase in their number (gingival hyperplasia). "Some of the polymorphisms associated with enhancement in special periodontal conditions as in case of gingival overgrowth subjects, the CD14 260 and IL-10 haplotype have been associated with the microbial colonisation of red complex bacteria." (PMID 29760828, 2018).
glomerular diseases (1 paper, 2015). "Other ratios, like the urinary CD14/CD3 ratio, which has been reported as helpful in differential diagnosis of glomerular diseases did not yield any significant results." (PMID 25890061, 2015).
Hematuria (1 paper, 2021). The presence of blood in the urine. "SLE patients with low C3 levels (<85 mg/dL) and those with hematuria had lower percentages of the three subsets of CD14+PLT+ than patients with normal C3 levels (85–193 mg/dL) and those without hematuria, respectively." (PMID 33947017, 2021).
hemochromatosis (1 paper, 2010). A disorder of iron metabolism characterized by a triad of HEMOSIDEROSIS; LIVER CIRRHOSIS; and DIABETES MELLITUS. "First, we obtained a large quantity of blood (about 400 ml) from hemochromatosis subjects undergoing therapeutic phlebotomy and sterile sorted CD14+CD16+ cells." (PMID 20102624, 2010).
hemorrhagic stroke (1 paper, 2024). A stroke caused by a bleed on the brain. "For cases of hemorrhagic stroke, polymorphisms in collagen genes, TLR4 and CD14 and even the gene that gives rise to C-reactive protein were identified." (PMID 38478535, 2024).
Hepatic hemangioma (1 paper, 2019). A congenital vascular malformation in the liver composed of masses of blood vessels that are atypical or irregular in arrangement and size. "We found that the percentage of CD14+HLA-DR−/low MDSCs in the paracancer liver tissue of CRLM patients (n = 20) was higher than the hepatic hemangioma patients (n = 6) (3.4% ± 2.3% vs. 1.1% ± 0.5%, P = 0.032)." (PMID 31534132, 2019). "The immunosuppressive activity of CD14+HLA-DR−/low MDSCs from paracancer liver tissue of CRLM patients and hepatic hemangioma patients was evaluated." (PMID 31534132, 2019).
Histiocytosis (1 paper, 2022). An excessive number of histiocytes (tissue macrophages). "CD14+ monocyte expansion is associated with flares in ECD, independently of the monocyte count in histiocytosis." (PMID 35687294, 2022).
HIV-associated neurocognitive disorder (1 paper, 2019). HIV-associated neurocognitive disorder (HAND) remains a common complication of HIV infection in the combination antiretroviral therapy (ART) era. "HIV infected CD14+CD16+ monocytes preferentially transmigrate across the blood-brain barrier (BBB) seeding the CNS viral reservoir in HIV-associated neurocognitive disorders (HAND)." (PMID 31867010, 2019).
Hypercalcemia (1 paper, 2021). An abnormally increased calcium concentration in the blood. "The expression of 1αOHase, CD14 and TLR4 was also observed in our case, and might represent the putative mechanism of hypercalcemia, thus treatment with high-dose corticoids was probably responsible for calcitriol secretion control." (PMID 35154010, 2021).
hyperhomocysteinemia (1 paper, 2021). A serious metabolic condition caused by mutations in the MTHFR gene, medications, or nutritional deficiency. "Ly6Chigh MC is the pro-inflammatory subset and the counterpart of human CD14++CD16+ intermediate MC which contributes to systemic and tissue inflammation in various metabolic disorders, including hyperhomocysteinemia (HHcy)." (PMID 33717169, 2021).
Hyperkeratosis (1 paper, 2002). Hyperkeratosis is a histopathological term defining a thickened stratum corneum and may be present in many different skin conditions, with many possible overlaps. "The infiltrate in mild dysplasia was similar to hyperkeratosis in the population of the B lymphocytes, although T cells and CD14 positive cells were more abundant in mild dysplasia." (PMID 11986779, 2002).
hyperlipoproteinemia (1 paper, 2022). An elevated concentration of lipoproteins. "The activation of the innate immune system in patients with hyperlipoproteinemia(a) is consistent with our recent study, which demonstrated that in patients with an elevated Lp(a) concentration, there is a redistribution of monocyte subpopulations towards an increase in CD14+CD16++ monocytes." (PMID 35207757, 2022).
hypersplenism (1 paper, 2024). Overactive functioning of the spleen, resulting in excessive destruction of blood cells. "This study used CD14 magnetic bead sorting of monocyte-macrophages showed high specificity, and high-purity macrophages were obtained from patients with normal traumatic spleen and splenic hypersplenism (92.24% and 89.94%)." (PMID 39620221, 2024).
idiopathic intracranial hypertension (1 paper, 2024). "Thus, we first compared CD14-positive immune cells in the cerebral venous sinus of patients with sub-acute cerebral venous sinus thrombosis and patients with idiopathic intracranial hypertension." (PMID 39605979, 2024).
insomnia (1 paper, 2021). A sleep disorder characterized by difficulty in falling asleep and/or remaining asleep. "We hypothesized that insomnia symptoms would be associated with higher circulating levels of the monocyte activation marker soluble CD14 (sCD14), the inflammatory marker interleukin-6 (IL-6), and the coagulation marker D-dimer." (PMID 33561176, 2021).
insulinomas (1 paper, 2016). "We have recently demonstrated the importance and synergestic role of LDR in tumor infiltration of CD14+ MΦ in irraidated insulinomas, LPS induced expression of iNOS and generation of NO in MΦ from late stage insulimoa bearing mice." (PMID 27511884, 2016).
intrahepatic cholestasis (1 paper, 2022). A cholestasis characterized by impairment of the bile flow caused by obstruction located in the liver. "In terms of BA, intrahepatic cholestasis controls and normal controls, ‘intermediate’ CD14++CD16+ Mo accounted for 4.81%, 4.67% and 1.63%, respectively; and sMac accounted for 6.72%, 5.53% and 0.06%, respectively (p < .0001), and pDC accounted for 1.43%, 4.94% and 3.55%, respectively (p < .0001)." (PMID 36333281, 2022).
invasive breast carcinoma (1 paper, 2025). A carcinoma that infiltrates the breast parenchyma. "Blood samples were obtained before and after neoadjuvant therapy from 30 patients with invasive breast cancer, and the expression of CD14 and CD16 was assessed via flow cytometry." (PMID 39955339, 2025).
ischemic cardiomyopathies (1 paper, 2021). "However, as it was shown that the majority of heart resident human CD68+ macrophages co-express CD14 in dilated and ischemic cardiomyopathies, we applied CD86 and CD163 as additional markers for M1 and M2 macrophages, respectively." (PMID 33432417, 2021).
juvenile xanthogranuloma (1 paper, 2017). A benign histiocytic tumor that occurs during childhood; it is distinct from Langerhans cell histiocytosis. "Juvenile xanthogranuloma (JXG) is a rare non-Langerhans cell (LCH) histiocytic disorder with histologic features characteristic of dermal dendrocytes (fascin+, CD1a−, CD207−) and macrophages (CD14+, CD68+, CD163+, and factor XIIIa+)." (PMID 28512266, 2017).
kidney inflammation (1 paper, 2025). "Single and combined inhibition of C5 and CD14 efficiently prevented BD-induced systemic inflammation and reduced local kidney inflammation in a mouse model." (PMID 40707525, 2025).
Krebs 2 carcinoma (1 paper, 2022). "The obtained data confirmed the strong overexpression of Mreg, Prg4, Col3a1, Selp, Marco, and Fgfr1 genes in Krebs-2 carcinoma, as well as Cdh11, Col4a5, Vcam1, Megf6, Scarf2, Scart1, and Cd14 genes in HH47." (PMID 36555446, 2022).
Langerhans cell histiocytosis (1 paper, 2015). Langerhans cell histiocytosis (LCH) is a systemic disease associated with the proliferation and accumulation (usually in granulomas) of Langerhans cells in various tissues. "Langerhans cell histiocytosis (LCH) is a dendritic cell disorder that results from clonal proliferation of functionally immature rounded LCH cells that express the monocyte marker CD14." (PMID 26697250, 2015).